DHH (desert hedgehog signaling molecule)
Description:
[Desert hedgehog protein]: Precursor of desert hedgehog, a morphogen that activates the smoothened signaling pathway, and which is essential for a variety of patterning events during development (By similarity). The C-terminal part of the precursor displays an autoproteolysis and a cholesterol transferase activity, resulting (1) in the cleavage of the full-length protein into two parts, desert hedgehog protein N-product and C-product and (2) covalent attachment of a cholesterol moiety to the C-terminus of the newly generated N-product (DHH-N) (By similarity). Both autoproteolysis and a cholesterol transferase activities occur in the endoplasmic reticulum (By similarity). Following additional lipidation, DHH-N acts as a morphogen, while the C-product is degraded in the endoplasmic reticulum (By similarity). [Desert hedgehog protein N-product]: The dually lipidated desert hedgehog protein N-product is a morphogen that activates the smoothened signaling pathway, and which is essential for a variety of patterning events during development (By similarity). Acts by binding to the patched receptor (PTCH1 or PTCH2), relieving smoothened (SMO) inhibition by patched, activating the smoothened signaling pathway and transcription of target genes. In the absence of DHH, patched represses the constitutive signaling activity of SMO (By similarity). DHH plays a key role in male gonad development (spermatogenesis) and the formation of Schwann cells (By similarity). Required for normal testis development and spermatogenesis, namely for the formation of adult-type Leydig cells and normal development of peritubular cells and seminiferous tubules (By similarity). In Schwann cells, controls the development of the peripheral nerve sheath and the transition of mesenchymal cells to form the epithelium-like structure of the perineurial tube (By similarity). May induce motor neurons in lateral neural tube and may have a polarizing activity. Involved in tissue regeneration: secreted from epithelial neuroendocrine cells and elicits a regenerative response from mesenchymal cells (By similarity). Functions in cell-cell mediated juxtacrine signaling. Activates primary cilia signaling on neighboring valve interstitial cells through a paracrine mechanism (By similarity). Promotes endothelium integrity.
Synonyms: HHG-3; MGC35145; GDMN; GDXYM; SRXY7
Tractability: Antibody: UniProt places it where antibodies can reach, with high confidence; its Gene Ontology location is reachable by antibodies, with high confidence; UniProt predicts a signal peptide or a membrane-spanning region.
Gene: Protein-coding gene on chromosome 12 (49,086,656 to 49,094,801, reverse strand). Ensembl gene ENSG00000139549.
Subcellular location: Endoplasmic reticulum membrane (Desert hedgehog protein); Golgi apparatus membrane; Secreted (Desert hedgehog protein N-product); Cell membrane
Pathways (Reactome):
Signal Transduction: Activation of SMO; Class B/2 (Secretin family receptors); Hedgehog 'on' state; Hedgehog ligand biogenesis; Ligand-receptor interactions; Release of Hh-Np from the secreting cell
Developmental Biology: Transcriptional regulation of testis differentiation
Disease: HHAT G278V doesn't palmitoylate Hh-Np
Gene Ontology:
Molecular function: calcium ion binding; patched binding; protein binding; zinc ion binding; cholesterol-protein transferase activity; endopeptidase activity; morphogen activity
Biological process: smoothened signaling pathway; cell fate specification; protein autoprocessing; regulation of gene expression; tissue regeneration; cell-cell signaling; myelination; positive regulation of smoothened signaling pathway; response to estradiol; response to estrogen; spermatid development
Cellular component: extracellular region; plasma membrane; endoplasmic reticulum membrane; Golgi membrane
Genetic constraint (gnomAD): Loss-of-function variants: 16 observed, 24.33 expected, observed/expected ratio (o/e) 0.66, 90% interval 0.44 to 1. The upper end of that interval is the gene's LOEUF score, 1, which puts it in group 4 of 6, group 1 being the genes least tolerant of losing a copy. Missense variants: 436 observed, 525.45 expected, observed/expected ratio (o/e) 0.83, 90% interval 0.77 to 0.9. Synonymous variants: 289 observed, 243.17 expected, observed/expected ratio (o/e) 1.19, 90% interval 1.08 to 1.31.
Homologues: Orthologues: chimpanzee DHH (100% identical), macaque DHH (99% identical), dog DHH (97% identical), pig DHH (97% identical), guinea pig DHH (97% identical), mouse Dhh (96% identical), rat Dhh (96% identical), rabbit DHH (84% identical), tropical clawed frog dhh (64% identical), zebrafish ihha (54% identical), zebrafish ihhb (54% identical), Drosophila melanogaster hh (51% identical), and 19 more. Paralogues in human: SHH (59% identical), IHH (58% identical).
Diseases named in the same sentence as DHH in open-access papers:
DHH is named in the same sentence as 36 diseases in open-access papers, as found by Europe PMC text mining. Sharing a sentence is not in itself a finding about the gene and the disease. The quoted sentences say what the papers report.
Swyer syndrome (3 papers, 2020 to 2025). "Depending on the genetic cause (primarily due to mutations in SRY, DHH (desert hedgehog), MAP3K1, or NR5A1), one of the co-morbidities of Swyer syndrome is neuropathy." (PMID 33183347, 2020). "Swyer syndrome may be caused by SRY mutation (10%–15%), FTHL17, STARD8, SOX9, MAP3K1, NR5A1, and desert hedgehog gene (DHH) mutation as well as other unidentified genes." (PMID 41163677, 2025). "Considering the risk of malignancy in gonads in patients with Swyer syndrome, the data suggest that some pathogenic variants (FTLHL17, DAX-1, DHH R124Q, del at 17q24.3) may be associated with a higher risk and some (STAR, STARD8, MAP3K1) with a lower risk of tumorigenesis." (PMID 38337479, 2024).
Infertility (2 papers, 2023 to 2024). "Interestingly, knockout of both IHH and DHH genes in mice decreased steroidogenesis and caused infertility." (PMID 39468655, 2024). "It has been reported that the loss of both DHH and IHH in GC results in the failure of theca cell (TC) development, defective steroidogenesis, and infertility in female mice." (PMID 36766700, 2023). "Mice lacking the expression of both DHH and IHH in GCs (DhhKO; IhhKO) fail to develop the TC cells, and suffer from impaired steroidogenesis and infertility due to failure of ovulation." (PMID 36766700, 2023).
mesothelioma (2 papers, 2014 to 2019). A usually malignant and aggressive neoplasm of the mesothelium which is often associated with exposure to asbestos. "Interestingly, DHH is the ligand whose expression is maintained in these conditions in several human and rodent mesothelioma models." (PMID 31788004, 2019). "The reason for a differential expression of DHH in mesothelioma is not clear, especially because it is mostly associated with testis and Schwann cell development." (PMID 31788004, 2019). "Moreover, in situ hybridization analysis of mesothelioma tumors showed similar results that the expression of SHH and DHH was mostly associated with the tumor cells." (PMID 25422081, 2014).
polyneuropathy (2 papers, 2016 to 2025). A disease or disorder affecting more than one nerve. "Mutations in the DHH gene have been associated with partial gonadal hypoplasia with micronucleus polyneuropathy." (PMID 39943208, 2025). "We identified seven patients with eight previously undescribed DHH missense variants (none were reported to have polyneuropathy)." (PMID 27899157, 2016).
Adrenal insufficiency (1 paper, 2013). Insufficient production of steroid hormones (primarily cortisol) by the adrenal glands. "Complete sex reversal in 46,XY males without adrenal insufficiency can also occur in conditions such as Leydig cell hypoplasia or due to mutations in SRY, DHH, SOX9, DMRT1, WNT1, or ATRX." (PMID 23748066, 2013).
basal cell carcinoma (1 paper, 2010). A carcinoma involving the basal cells. "HHIP antagonizes all three of the hedgehog family of ligands (SHH, DHH and IHH) and has been shown to be down-regulated in numerous epithelial tumor types with the notable exception of basal cell carcinoma where it is upregulated." (PMID 20860831, 2010).
breast tumour (1 paper, 2018). "Significant over expression of SHH (R.E = 4.4 ± 3.32), DHH (R.E = 4.7 ± 3.46), PTCH1 (R.E = 3.4 ± 3.08) and GLI1 (R.E = 3.8 ± 2.49) were detected in the breast tumour biopsies as compared with controls." (PMID 29329585, 2018).
co-infection (1 paper, 2025). "Gills expressed upregulation of DHH in response to co-infection." (PMID 40943072, 2025).
cryptorchidism (1 paper, 2015). The failure of one or both testes of a male fetus to descend from the abdomen into the scrotum during the late part of pregnancy. "Whether down regulated expression of DHH or increased insulin levels in umbilical cord blood can cause cryptorchidism in newborn males is unclear." (PMID 25798927, 2015).
dysplasia (1 paper, 2021). A usually neoplastic transformation of the cell, associated with altered architectural tissue patterns. "DHH gene mutation can cause 46, XY partial gonadal dysplasia." (PMID 34276780, 2021).
endothelial dysfunction (1 paper, 2018). In vascular diseases, endothelial dysfunction is a systemic pathological state of the endothelium (the inner lining of blood vessels) and can be broadly defined as an imbalance between vasodilating and vasoconstricting substances produced by (or acting on) the endothelium. "Reduced desert hedgehog (DHH) expression by the Schwann cells further contributes to nerve fiber loss and conduction velocity impairment, which together with induced endothelial dysfunction contribute to the development of DN." (PMID 29770116, 2018).
experimental autoimmune encephalomyelitis (1 paper, 2020). An autoimmune demyelinating disease of the central nervous system that is produced experimentally in animals by the injection of homogenized brain or spinal cord in Freund's adjuvant. "We first characterized DHH expression within endothelial cells at the BBB, then demonstrated that DHH is down-regulated during experimental autoimmune encephalomyelitis (EAE)." (PMID 33253145, 2020).
glioblastoma (1 paper, 2015). The most malignant astrocytic tumor (WHO grade IV). "Collectively, our data unveil a role for DHH in exacerbated tumor angiogenesis and permeability, which may ultimately favor glioblastoma growth, and thus place the DHH/Ptch2 nexus as a molecular target for novel therapies." (PMID 26635611, 2015).
gonadal dysgenesis (1 paper, 2021). A congenital disorder characterized by the presence of extremely hypoplastic gonads preventing the development of secondary sex characteristics. "We speculate that the p.Pro288Arg variant diminishes autoproteolysis activity of the DHh-C domain of DHH protein that lead to the clinical condition 46,XY gonadal dysgenesis (GD) or 46,XY sex reversal 7 in our patient." (PMID 33594065, 2021).
hypospadias (1 paper, 2016). Hypospadias is the displacement of the urethral meatus on the ventrum of the penis. "In the case of MAP3K1, DHH, and ZFPM2 it is difficult to distinguish whether variants identified in patients categorized as isolated hypospadias expand the known mutation spectrum of these genes or whether these patients have underlying gonadal dysgenesis." (PMID 27899157, 2016).
leukemia (1 paper, 2013). A malignant (clonal) hematologic disorder, involving hematopoietic stem cells and characterized by the presence of primitive or atypical myeloid or lymphoid cells in the bone marrow and the blood. "Interestingly, DHH-RHEBL1-positive patients showed higher expression of several genes known to be associated with leukemia occurrence and/or tumor progression, such as FLT3, BEX1, MUC4 and AFAP1L2." (PMID 24127550, 2013).
male infertility (1 paper, 2025). The inability of the male to effect fertilization of an ovum after a specified period of unprotected intercourse. "For instance, synonymous substitutions in the desert hedgehog (DHH) gene from DSD had a reproductive impact contributing to male infertility and gonadal dysgenesis." (PMID 40043094, 2025).
osteosarcoma (1 paper, 2023). A usually aggressive malignant bone-forming mesenchymal neoplasm, predominantly affecting adolescents and young adults. "Variable expression of IHH, DHH and SHH mRNA was detected in all human osteosarcoma cell lines." (PMID 37845394, 2023).
schwannoma (1 paper, 2013). A benign, usually encapsulated slow growing tumor composed of Schwann cells. "However, BFABP, DHH, P0, PMP22 and PLP are not overexpressed in schwannomas or neural crest cells, but only in Schwann cell precursors." (PMID 23354516, 2013).
tumor (7 papers, 2013 to 2025). "NR5A1 regulates other target genes, such as SRY, responsible for testicular differentiation, WT1, and DHH, associated with gonadal abnormalities and increased risk of tumor." (PMID 41303802, 2025). "However, DHH loss-of-function in BTICs had a dramatic effect on tumor growth, as sh2 and sh4 clones produced tumors four times smaller than controls." (PMID 26635611, 2015). "Over expression of SHH, DHH and GLI1 were associated with cell grades in Finak dataset and also related with poorly differentiated tumours." (PMID 29329585, 2018). "Finally, DHH knockdown in BTICs dramatically reduced tumor formation and growth, as well as intra-tumor permeability." (PMID 26635611, 2015). "Finally, DHH silencing in BTICs dramatically reduced tumor growth, as well as vascularization and intra-tumor permeability." (PMID 26635611, 2015). "Overall, our work unveils a role for DHH in heightened tumor angiogenesis and permeability, which may ultimately favor GBM progression, and thus places the DHH/Ptch2 nexus as a putative target for novel therapies directed against malignant stem-cell niches in GBM." (PMID 26635611, 2015). "Mean mRNA values of SHH, DHH and GLI1 showed gradual increase with tumour size, nodal spread and distant metastasis." (PMID 29329585, 2018). "PTCH1, SHH, DHH, and GLI1 over-expression were observed in 74%, 95%, 92% and 98% tumour specimens of the cohort." (PMID 29329585, 2018). "SHH, DHH, PTCH1 and GLI1 were significantly over-expressed in tumours as compared with respective normal mammary tissues." (PMID 29329585, 2018). "A significant correlation of SHH, DHH and GLI1 expression with advanced tumour size, stages, grades, nodal involvement and distant metastasis was observed (p < 0.05)." (PMID 29329585, 2018). "Over-expression of SHH, DHH and GLI1 was significantly correlated with advanced stages and tumour grades of the cohort." (PMID 29329585, 2018). "Significant correlation was observed between SHH (R.E = 12.76 ± 5.12, p < 0.0001), DHH (R.E = 9.8 ± 5.1, p < 0.05) and GLI1 (R.E = 12.3 ± 3.9, p < 0.0001) and invasive tumour size." (PMID 29329585, 2018). "The results of the present study indicated the gene expression of these important factors in the Hedgehog signaling pathway, such as DHH, GLI1, and PTCH1, was changed by the knockdown of AE1, suggesting that AE1 regulates the tumor behavior of ESCC via this pathway." (PMID 28160546, 2017). "Furthermore, given the correlation between high DHH and GLI1 expression and higher stromal content of human PCa samples, we hypothesized that increasing stromal HH signaling would decrease tumor progression by maintaining or increasing SM." (PMID 27935821, 2017).
cancer (4 papers, 2013 to 2025). A tumor composed of atypical neoplastic, often pleomorphic cells that invade other tissues. "These drugs, such as Cyclopamine, Vismodegib etc. are only effective when a cancer cell with excessive Hedgehog pathway activation, is encountering over-expressed hedgehog ligands (SHH, IHH or DHH) or has mutated PTCH1 or SMO in membrane." (PMID 23935937, 2013). "This suggests that DHH plays an important role in the reproductive system and the development of some tumors, as well as drug interventions targeting DHH signaling pathways, may become potential strategies for the treatment of cancer." (PMID 39900571, 2025). "Interestingly, both DHH and RHEBL1 genes have been implicated in a variety of human diseases, including cancer." (PMID 24127550, 2013).
benign tumors (1 paper, 2009). "HH signaling in GN could be mediated by DHH, which, like GLI1 and GLI3 is differentially expressed in these benign tumors." (PMID 19834598, 2009).
infection (1 paper, 2025). The state of being infected such as from the introduction of a foreign agent such as serum, vaccine, antigenic substance or organism. "The potential expression of DHH in peripheral tissues such as the skin or gills during infection may indicate a role in tissue regeneration or immune modulation." (PMID 40943072, 2025).
peripheral neuropathy (1 paper, 2018). A disorder affecting the peripheral nervous system. "It is only with the diagnosis of DHH mutation that we were prompted to consider peripheral neuropathy in our patient." (PMID 29507583, 2018). "Gonadal tumours and peripheral neuropathy have been associated with DHH mutations." (PMID 29507583, 2018).
DHH also shares sentences with these, for which no sentence is quoted: acute myeloid leukemia (1 paper); adrenal hypoplasia (1); Bardet-Biedl syndrome (1); chronic myelogenous leukemia (1); depression (1); epidermoid carcinoma (1); Leigh syndrome (1); melanoma (1); mucolipidosis (1); multiple sclerosis (1); neuropathy (1); Spastic paraplegia (1).